Y_RNA (Y RNA )
Gene: Miscellaneous RNA gene on chromosome 3 (106,688,678 to 106,688,779, forward strand). Ensembl gene ENSG00000200361.
Homologues: Orthologues: chimpanzee Y_RNA (96% identical), macaque Y_RNA (93% identical). Paralogues in human: RNY3 (91% identical), Y_RNA (89% identical), RNY3P1 (88% identical), Y_RNA (88% identical), Y_RNA (87% identical), Y_RNA (86% identical), RNY3P14 (85% identical), RNY3P4 (85% identical), Y_RNA (85% identical), Y_RNA (84% identical), RNY3P11 (83% identical), RNY3P16 (83% identical), and 97 more.